CHEK1 (checkpoint kinase 1)
Description:
Serine/threonine-protein kinase which is required for checkpoint-mediated cell cycle arrest and activation of DNA repair in response to the presence of DNA damage or unreplicated DNA. May also negatively regulate cell cycle progression during unperturbed cell cycles. This regulation is achieved by a number of mechanisms that together help to preserve the integrity of the genome. Recognizes the substrate consensus sequence [R-X-X-S/T]. Binds to and phosphorylates CDC25A, CDC25B and CDC25C. Phosphorylation of CDC25A at 'Ser-178' and 'Thr-507' and phosphorylation of CDC25C at 'Ser-216' creates binding sites for 14-3-3 proteins which inhibit CDC25A and CDC25C. Phosphorylation of CDC25A at 'Ser-76', 'Ser-124', 'Ser-178', 'Ser-279' and 'Ser-293' promotes proteolysis of CDC25A. Phosphorylation of CDC25A at 'Ser-76' primes the protein for subsequent phosphorylation at 'Ser-79', 'Ser-82' and 'Ser-88' by NEK11, which is required for polyubiquitination and degradation of CDCD25A. Inhibition of CDC25 leads to increased inhibitory tyrosine phosphorylation of CDK-cyclin complexes and blocks cell cycle progression. Also phosphorylates NEK6. Binds to and phosphorylates RAD51 at 'Thr-309', which promotes the release of RAD51 from BRCA2 and enhances the association of RAD51 with chromatin, thereby promoting DNA repair by homologous recombination. Also promotes repair of DNA cross-links through phosphorylation of FANCE. Binds to and phosphorylates TLK1 at 'Ser-743', which prevents the TLK1-dependent phosphorylation of the chromatin assembly factor ASF1A. This may enhance chromatin assembly both in the presence or absence of DNA damage. May also play a role in replication fork maintenance through regulation of PCNA. May regulate the transcription of genes that regulate cell-cycle progression through the phosphorylation of histones (By similarity). Phosphorylates histone H3.1 (to form H3T11ph), which leads to epigenetic inhibition of a subset of genes (By similarity). May also phosphorylate RB1 to promote its interaction with the E2F family of transcription factors and subsequent cell cycle arrest. Phosphorylates SPRTN, promoting SPRTN recruitment to chromatin. Reduces replication stress and activates the G2/M checkpoint, by phosphorylating and inactivating PABIR1/FAM122A and promoting the serine/threonine-protein phosphatase 2A-mediated dephosphorylation and stabilization of WEE1 levels and activity. [Isoform 2]: Endogenous repressor of isoform 1, interacts with, and antagonizes CHK1 to promote the S to G2/M phase transition.
Synonyms: CHK1; OZEMA21
Tractability: Small molecule: a drug acting on it is in phase 2 or 3 trials; a structure with a bound ligand is known; a high-quality ligand is known; it has a high-quality binding pocket; it belongs to a druggable protein family. PROTAC: it is named in the literature on targeted protein degradation; UniProt records ubiquitination sites on it; ubiquitination databases record sites on it; a small molecule that binds it is known.
Target class: Kinase; Protein Kinase; Enzyme; CAMK protein kinase CAMK1 family; CAMK protein kinase CHK1 subfamily; CAMK protein kinase group
Chemical probes: CCT244747 (high quality), CHEMBL2381116, CHEMBL398606, GNE-900, PD005452, PD080781, PD080953, PD081153, PD081259, PD081354, PD081384, PD081492, PD081801, PD081835, PD081911, PD082053, PD082079, PD082216, PD082424, PD082446, and 47 more
Gene: Protein-coding gene on chromosome 11 (125,625,163 to 125,676,255, forward strand). Ensembl gene ENSG00000149554.
Subcellular location: Nucleus; Chromosome; Cytoplasm; Cytoplasm, cytoskeleton, microtubule organizing center, centrosome
Subcellular location (Human Protein Atlas): Nucleoplasm; Vesicles
Pathways (Reactome):
Cell Cycle: Activation of ATR in response to replication stress; Chk1/Chk2(Cds1) mediated inactivation of Cyclin B:Cdk1 complex; G2/M DNA damage checkpoint; Ubiquitin-Mediated Degradation of Phosphorylated Cdc25A
Gene expression (Transcription): Transcriptional Regulation by E2F6
DNA Repair: Presynaptic phase of homologous DNA pairing and strand exchange; Processing of DNA double-strand break ends
Signal Transduction: Signaling by SCF-KIT
Gene Ontology:
Molecular function: histone H3T11 kinase activity; protein binding; protein domain specific binding; protein kinase activity; protein serine kinase activity; protein serine/threonine kinase activity; ATP binding
Biological process: cellular response to mechanical stimulus; DNA damage checkpoint signaling; DNA damage response; DNA repair; mitotic G2 DNA damage checkpoint signaling; mitotic G2/M transition checkpoint; negative regulation of mitotic nuclear division; positive regulation of cell cycle; regulation of double-strand break repair via homologous recombination; regulation of mitotic centrosome separation; signal transduction in response to DNA damage; chromatin remodeling; DNA replication; negative regulation of G0 to G1 transition; negative regulation of gene expression, epigenetic; replicative senescence; negative regulation of cell cycle phase transition
Cellular component: centrosome; chromosome; chromosome, telomeric region; condensed nuclear chromosome; cytoplasm; extracellular region; nucleoplasm; nucleus; protein-containing complex; chromatin; cytosol; replication fork
Genetic constraint (gnomAD): Loss-of-function variants: 24 observed, 40.61 expected, observed/expected ratio (o/e) 0.59, 90% interval 0.43 to 0.83. The upper end of that interval is the gene's LOEUF score, 0.83, which puts it in group 3 of 6, group 1 being the genes least tolerant of losing a copy. Missense variants: 321 observed, 440.44 expected, observed/expected ratio (o/e) 0.73, 90% interval 0.66 to 0.8. Synonymous variants: 134 observed, 148.55 expected, observed/expected ratio (o/e) 0.9, 90% interval 0.78 to 1.04.
Gene-disease validity (ClinGen):
ClinGen rates the evidence that CHEK1 causes each of these diseases.
familial ovarian cancer (autosomal dominant): No Known Disease Relationship. An instance of ovarian cancer that is caused by an inherited modification of the individual's genome.
hereditary breast carcinoma (autosomal dominant): No Known Disease Relationship. Breast carcinoma that has developed in relatives of patients with history of breast carcinoma.
Homologues: Orthologues: macaque CHEK1 (98% identical), pig CHEK1 (97% identical), dog CHEK1 (96% identical), mouse Chek1 (93% identical), rat Chek1 (93% identical), chimpanzee CHEK1 (81% identical), tropical clawed frog chek1 (78% identical), zebrafish chek1 (55% identical), Drosophila melanogaster grp (49% identical).
Diseases named in the same sentence as CHEK1 in open-access papers:
CHEK1 is named in the same sentence as 226 diseases in open-access papers, as found by Europe PMC text mining. Sharing a sentence is not in itself a finding about the gene and the disease. The quoted sentences say what the papers report.
breast carcinoma (208 papers, 2005 to 2026). "Immunohistochemistry analysis confirmed the overexpression of CHEK1 protein in breast cancer tissues, suggesting potential diagnostic and prognostic significance for CHEK1 in breast cancer." (PMID 39473450, 2024). "High expression of CHEK1 in Nigerian human breast cancer patients is associated with an aggressive phenotype and poor prognosis." (PMID 38951817, 2024). "Even less is known about the association of ATR/CHEK1 mutations, either germ line or somatic, with breast cancer incidence or outcome." (PMID 37390209, 2023). "Contrastingly, the result obtained in lung adenocarcinoma, ovarian cancer, and breast cancer suggested that high expression of CHEK1 is associated with poor survival rates." (PMID 32178478, 2020). "KSR1 expression is positively associated with breast cancer 1, early onset (BRCA1), BRCA1-associated ring domain 1 (BARD1) and checkpoint kinase 1 (Chk1) levels in breast cancer specimens." (PMID 26425651, 2015). "To date, a small number of gene-based association studies have been carried out to investigate the roles of ATR and CHEK1 as breast cancer susceptibility genes, using a tagging SNP (tagSNPs) approach." (PMID 23844225, 2013). "As a result, there was little evidence in our study supporting any inherited sequence variants in the CHEK1 region being associated with breast cancer risk or survival." (PMID 23844225, 2013). "We therefore used a tagging SNP (tagSNP) approach based on recent SNP data available from the 1000 genomes projects, to investigate the roles of ATR and CHEK1 in breast cancer risk and survival." (PMID 23844225, 2013). "Here, we have carried out a more detailed study of the role of the ATR and CHEK1 in breast cancer risk and survival based on the more complete resources now available from the 1000 genomes project." (PMID 23844225, 2013). "Conversely, deletion of the distal end of chromosome 11q, defined as downregulation of the marker Chk1 (checkpoint kinase 1), was associated with an impaired tamoxifen response, and with low proliferative breast cancer of low grade." (PMID 18823530, 2008). "Indeed, irradiated breast cancer cells can release EVs able to activate checkpoint kinase 1 (Chk1), histone H2AX, and ataxia telangiectasia mutated (ATM) in recipient cells, thus triggering DNA repair responses." (PMID 33670185, 2021). "Moreover, expression of higher levels of quiescence and dormancy-associated genes, including CDKN1B and CHEK1, was observed in highly metastatic breast cancer cells considered to be tumor-initiating cells (TICs) with stem-like properties." (PMID 27845900, 2017). "Also, some meta-analysis studies found that SNPs in genes MDR, MTR, SLC4A7, ATR and CHEK1 were significantly associated with breast cancer susceptibility." (PMID 24386390, 2013). "However, we conclude there is little evidence to support any role for common SNPs in the ATR and CHEK1 regions in breast cancer risk or survival." (PMID 23844225, 2013). "However, deletion of distal chromosome 11q, defined as downregulation of the marker Chk1 (checkpoint kinase 1), was associated with an impaired tamoxifen response, and interestingly with low proliferative breast cancer of low grade." (PMID 18823530, 2008). "However, whether mutations in ATR/CHEK1 contribute to evolution of specific subtypes of breast cancer or to disease progression remains uncertain." (PMID 37390209, 2023). "Clinical studies have demonstrated that the CHEK1 inhibitor AZD7762 synergizes with CDK4/6 inhibitors in HR+ breast cancer models, highlighting the potential of CHEK1 as a cross-subtype therapeutic target." (PMID 40344565, 2025). "Recent evidence, however, suggests that CHEK1 also plays a critical role in hormone receptor-positive (HR+) breast cancer subtypes, particularly LumA and LumB." (PMID 40344565, 2025).
breast carcinoma (continued). "We then confirmed the inhibitory potency of hsa‐miR‐195‐5p towards CHEK1 in ER− and ER+ breast cancer cell lines and explored the ability of specific CHEK1 inhibitors to modulate doxorubicin efficacy in vitro." (PMID 40548926, 2025). "For instance, no publications were found on PubMed using the keywords “pathomics”, “CHEK1”, and “breast cancer”." (PMID 40344565, 2025). "In luminal (ER+) breast carcinoma (BC), miRNA profiling identified miR‐195‐5p as a key regulator of proliferation that targets CHEK1, CDC25A, and CCNE1." (PMID 40548926, 2025). "As a result, reduced survival rates of patients with high CHEK1 expression were reported in bladder, brain, lung, ovary, and breast cancers." (PMID 39456660, 2024). "In this study, it was also found that the decrease in mRNA levels for several other key DNA repair proteins, including BRCA2 (Breast Cancer Gene 2), CHK1 (Checkpoint kinase 1), CHK2 (Checkpoint kinase 2), Rad51, and ATR, was caused by long-term exposure to Al." (PMID 39795956, 2024). "On the other hand, for breast cancer cells cocultured with in vitro differentiated murine adipocytes, a significant increase in IL-6 expression was observed, which elevated checkpoint kinase 1 (Chk1) phosphorylation and promoted radioresistance in tumor cells." (PMID 36670988, 2023). "Recently, the Breast Cancer Consortium highlighted the necessity to also treat variant in other genes, including among others ATM, CHEK1, and CHEK2, in a similar manner to BRCA alterations, given their important influence on breast cancer development." (PMID 36753055, 2023). "Only CHK1, a protein encoded by CHEK1, was overexpressed in basal-like breast cancer subtype versus HER2-positive, luminal A, and luminal B." (PMID 36547059, 2022). "Upregulation of CHEK1 is involved in various types of cancer and promotes tumor progression via affecting cell cycle and DNA damage response including breast cancer, pancreatic cancer, and oral squamous cell carcinoma." (PMID 34545328, 2021). "CHEK1 in breast cancer is also a notable regulator of the response to DNA damage, which is over-expressed in triple-negative breast cancer (TNBC) and has therefore been proposed as a potential target for treatment." (PMID 34115745, 2021). "CHEK1 is a serine–threonine protein kinase that regulates EMT through ZEB1-mediated signaling in breast cancer cells." (PMID 34455105, 2021). "Breast cancer exosomes promote DNA damage repair responses after radiation by regulating the phosphorylation of checkpoint kinase 1 (Chk1)." (PMID 34899907, 2021). "The probability of a reduced survival rate is greater for patients with high CHEK1 gene expression in bladder, brain, lung, ovary, and breast cancers as compared with patients with low CHEK1 expression." (PMID 32178478, 2020). "In breast cancer, CHEK1 mRNA expression and phosphorylated CHEK1 protein have demonstrated prognostic value in breast cancer-related death." (PMID 32133296, 2020). "CHEK1 is highly expressed in breast cancer, colon cancer, liver cancer, gastric cancer and other tumors, and CHEK1-related signaling pathways have been confirmed in a wide variety of tumors." (PMID 32391047, 2020). "After exposure to irradiation, breast cancer exosomes led to an increased phosphorylation of ataxia telangiectasia mutated (ATM), Histone H2AX and checkpoint kinase 1 (Chk1) in recipient cells indicating the induction of DNA damage repair responses." (PMID 30925921, 2019). "Inhibition of Hsp90 leads to the degradation of BRCA2 (breast cancer 2), Rad51, and CHK1 (checkpoint kinase 1) and results in genomic instability." (PMID 30368549, 2019). "WEE1 is highly expressed in brain cancer, breast cancer, and melanoma, while CHEK1 expression is higher in the tumor tissues of breast cancer, colon cancer, and liver cancer." (PMID 31387297, 2019). "Previous studies in breast cancer as well as in leukemia and lymphoma have shown that CHEK1 inhibition can be characterized by an increased level of pH2AX (Ser139)." (PMID 30543688, 2018).
breast carcinoma (continued). "A strong positive correlation was observed also between mRNA expressions of CHRNA5 and CHEK1 across breast cancer cell lines and tumors." (PMID 30543688, 2018). "Our results (based on PCR analysis and inhibition of cell growth) highlighted three specific mediators, namely CDC20, RAD51, and CHEK1, as therapeutic targets in breast cancer cells." (PMID 25763370, 2015). "Studies also suggest that miR-195 and CHEK1-related signal pathways have been involved in the sensitivity of chemotherapy to breast cancer, laryngeal cancer and colon cancer." (PMID 25840419, 2015). "In particular, sensitization to Docetaxel with CHEK1 antagonist PF-004477736 has been observed in colon and breast cancer xenografts." (PMID 24525428, 2014). "ATR and CHEK1 tagSNPs were genotyped in the Sheffield Breast Cancer Study (SBCS; 1011 cases and 1024 controls) using Illumina GoldenGate assays." (PMID 23844225, 2013). "DNA damage and replication checkpoints mediated by the ATR-CHEK1 pathway are key to the maintenance of genome stability, and both ATR and CHEK1 have been proposed as potential breast cancer susceptibility genes." (PMID 23844225, 2013). "The chromosome 11 interval containing the EI24 and CHEK1 genes is a frequently altered region in breast cancer." (PMID 23844225, 2013). "A molecular study of breast cancer tumour samples revealed a high frequency of deletions and promoter methylations in the EI24 and CHEK1 genes, and reported poor survival associations for patients with these alterations." (PMID 23844225, 2013). "Recent studies have emphasized the prognostic value of CHEK1 in breast cancer." (PMID 40344565, 2025). "Both evaluated miRNAs exhibited significant downregulation in breast carcinomas compared to adjacent mammary tissues and, in contrast, the expression of CHEK1, CDC25A and CCNE1 genes was significantly increased in malignant versus adjacent tissues (N = 18, P < 0.01 for all)." (PMID 40548926, 2025). "The study demonstrated that breast cancer cells expressing elevated levels of RNF126 exhibited heightened replication stress and increased sensitivity to CHEK1 inhibitors, providing further insights into the intricate associations between CHEK1, RNF126, and breast cancer outcomes." (PMID 39473450, 2024). "TDEs from breast cancer cells receiving radiotherapy triggered the DNA damage repair response (DDR) such as ataxia telangiectasia-mutation (ATM) by increasing the phosphorylation of histone H2AX and checkpoint kinase 1 (CHK1) in recipient cells." (PMID 36359776, 2022). "Besides, seven genes including BRCA1, FN1, CCNE1, CCND1, CHEK1, BUB3, and CDC25A were identified as the hub nodes by the PPI network, and CCNE1 and CHEK1 were confirmed to be related with the prognostic survival of the patients with breast cancer." (PMID 35186236, 2022). "Checkpoint Kinase 1 (CHK1) inhibitors were identified as potent inhibitors of MSL breast cancers." (PMID 31448050, 2019). "In addition, the correlation of mRNA expressions of CHRNA5 and CHEK1 among breast cancer cell lines and tumors was highly significant." (PMID 30543688, 2018). "Our findings reveal that CHRNA5 RNAi could act as a candidate CHEK1 inhibitor leading to enhanced drug sensitivity in breast cancer cells and warrants further studies in different cell lines and cancers." (PMID 30543688, 2018). "In addition, in breast cancer cells, cell survival following DNA damage depends on mTORC2-mediated Chk1 (checkpoint kinase 1) activation." (PMID 26404259, 2015). "We conclude that common alleles of ATR and CHEK1 are not implicated in breast cancer risk or survival, but we cannot exclude effects of rare alleles and of common alleles with very small effect sizes." (PMID 23844225, 2013).